RNU1-45P (RNA, U1 small nuclear 45, pseudogene)
Gene: Small nuclear RNA gene on chromosome 4 (178,116,721 to 178,116,861, reverse strand). Ensembl gene ENSG00000253000.
Homologues: Orthologues: chimpanzee U1 (99% identical), rabbit U1 (60% identical). Paralogues in human: RNU1-1 (66% identical), RNU1-2 (66% identical), RNU1-27P (66% identical), RNU1-28P (66% identical), RNU1-3 (66% identical), RNU1-4 (66% identical), RNVU1-18 (66% identical), RNVU1-29 (66% identical), RNVU1-7 (66% identical), U1 (66% identical), RNU1-67P (65% identical), RNU1-89P (65% identical), and 134 more.